COL1A2 (collagen type I alpha 2 chain)
Diseases named in the same sentence as COL1A2 in open-access papers (continued):
Sharing a sentence is not in itself a finding about the gene and the disease.
colitis (5 papers, 2017 to 2024). Inflammation of the colon. "Pirfenidone effectively reduced the deposition of collagen in colitis-associated fibrosis and significantly suppressed the mRNA expression of COL1A2, COL3A1, and TGFB1." (PMID 39684719, 2024). "Since excessive collagen deposition may lead to the development of intestinal fibrosis, FRB seemingly reduced the risk of fibrosis due to DSS-induced colitis, by reducing the mRNA expression of Col1a1 and Col1a2 and increasing the level of Mmp3." (PMID 34070845, 2021). "In a pre-clinical study, RXC008 demonstrated anti-fibrotic effects in adoptive T-cell transfer and chronic DSS murine models of colitis, suppressing fibrosis and reducing the expression of fibrotic markers such as COL1A1, COL1A2, and TGFB1." (PMID 39684719, 2024). "CSA13 treatment significantly inhibited colonic collagen Col1a2 mRNA expression and fibroblast accumulation (αSMA and vimentin) in the mice with TNBS colitis that was reversed by Fpr2 shRNA." (PMID 29180648, 2017).
dental fluorosis (5 papers, 2019 to 2025). A condition that results from excessive fluoride ingestion during tooth development, resulting in tooth discoloration ranging from white streaks to brown stains and cracks or pits in the tooth enamel. "The rs412777 polymorphism in the COL1A2 gene is associated with an increased risk of dental fluorosis in the Brazilian population, with the CC genotype associated with a higher risk and the A allele potentially having a protective effect." (PMID 40563416, 2025). "Significant association of COL1A2 (rs 412,777) polymorphism in the COL1A2 gene with dental fluorosis." (PMID 41355938, 2025).
dermatosparaxis (5 papers, 2019 to 2025). "Other types include kyphoscoliotic EDS (kEDS), which causes severe muscle weakness due to PLOD1 mutations, arthrochalasia EDS (aEDS) with extreme joint laxity resulting from COL1A1 or COL1A2 mutations, and dermatosparaxis EDS (dEDS) with fragile skin due to ADAMTS2 mutations." (PMID 40542421, 2025). "Minor ultrastructural changes may appear as serrated circles such as those from patients with arthrochalasia caused by COL1A2 mutations or mild dermatosparaxis." (PMID 36421833, 2022).
neurofibroma (5 papers, 2021 to 2025). An intraneural or extraneural neoplasm arising from nerve tissues and neural sheaths. "This is consistent with the observation that collagens such as COL1A1 and COL1A2, often associated with pro-fibrogenic skin fibroblasts, are downregulated in human neurofibromas." (PMID 37817770, 2023). "Ongoing studies are focused on determining whether targeting of sensory neuron-specific COL1A2 production will reduce neurofibroma growth." (PMID 35589737, 2022).
tendinopathy (5 papers, 2009 to 2025). "In line with aberrant matrix turnover generally featured in tendinopathy, the transcripts of the following genes were significantly increased in the tendinopathic samples: COL1A1, COL1A2, COL18A1." (PMID 39918402, 2025). "However, while the mRNA expression of a number of collagens was 1.6–2.7-fold upregulated in tendinopathy patients, COL1A1, COL1A2, COL10A1, and COL11A1/2 were 5.3–15.2-fold upregulated in tetraplegic CP patients, suggesting strongly increased collagen synthesis." (PMID 38001919, 2023).
achondroplasia (4 papers, 2020 to 2022). Achondroplasia is the most common form of chondrodysplasia, characterized by rhizomelia, exaggerated lumbar lordosis, brachydactyly, and macrocephaly with frontal bossing and midface hypoplasia. "People with a COL1A and COL1A2 genes mutation are more likely to develop a herniated disc, and an FGFR3 gene mutation rs28931614 (G > A, C) at position 4p:1804392 contributes to 100 percent development of achondroplasia." (PMID 36362274, 2022).
adenoma (4 papers, 2015 to 2025). A neoplasm arising from the epithelium. "In addition, the expression of COL1A2 was significantly elevated relative to adenoma and CIS, making it an excellent diagnostic biomarker for the adenocarcinoma CRC stage." (PMID 40362431, 2025). "Increased COL1a2 may result from the presence of cancer associated fibroblasts in FZD9-/- adenomas and is associated with poor prognosis." (PMID 35924166, 2022). "COL1A2 expression was significantly elevated in adenocarcinoma compared to CIS (p-value < 0.0001) as well as adenoma compared to CIS (p-value < 0.05)." (PMID 40362431, 2025). "ARRB1 (p = 2.79 × 10−5), CTBP1 (p = 1.33 × 10−5) and CTBP2 genes (p = 0.0002) exhibited notable upregulation in adenoma, whereas COL1A2 (p = 0.0075), CEBPZ (p = 0.0057), MED10 (p = 0.0196) and PAWR genes (p = 0.00215) showed significant upregulation in adenocarcinoma." (PMID 40362431, 2025). "No significant gene expression alterations could be detected in the stromal cells isolated from adenomas compared to the normals, but COL1A2, FADS1, MAL, PRIMA1, SULF1, THBS2, TIMP1 genes’ transcripts showed significant differences (p < 0.05) in logFc values for the tumour versus normal comparison." (PMID 26482433, 2015). "Among the identified molecular targets, ARRB1 was validated using RT-qPCR for adenoma, COL4A5 and RPS3A for CIS, and COL1A2 and MED10 for adenocarcinoma." (PMID 40362431, 2025). "Additionally, COL1A2 (p-value < 0.0001) and MED10 (p-value < 0.05) were significantly higher in the adenocarcinoma group compared to the adenoma group." (PMID 40362431, 2025). "Subsequent investigation revealed that the COL1A2 gene (p-value: 0.0064), though not ranked among the top 20 frequently occurring genes, emerged as a promising candidate biomarker with potential in distinguishing adenocarcinoma from CIS and adenoma." (PMID 40362431, 2025). "In addition, ALDH1A3, COL1A2, FADS1, SFRP2, SULF1, and THBS2 were found to be significantly (p < 0.01) differentially expressed in tumour samples but not in adenomas compared to healthy samples." (PMID 26482433, 2015).
Alzheimer disease (4 papers, 2019 to 2025). A progressive, neurodegenerative disease characterized by loss of function and death of nerve cells in several areas of the brain leading to loss of cognitive function such as memory and language. "(2019) reported that the Col1a2 gene, which is involved in the neurotrophin signaling pathway, is closely related to depression in Alzheimer's disease patients." (PMID 39295096, 2024). "In particular, genes such as Col1a1 Col1a2, Fmod, Ptgds, and Aldh1a2 are induced by exercise training and have been found to prevent hippocampal ageing in an Alzheimer’s disease model of animals with premature ageing." (PMID 31551509, 2019).
colon adenocarcinoma (4 papers, 2020 to 2025). "Studies have shown that Col1a2 is positively correlated with immune infiltration in colon adenocarcinoma and is considered a key immune-related gene in dilated cardiomyopathy." (PMID 41007677, 2025). "Gene set enrichment analysis of COL1A2 in colon adenocarcinoma." (PMID 36057263, 2022). "However, the specific role and mechanism of COL1A2 in colon adenocarcinoma (COAD) remain unclear." (PMID 37805556, 2023). "For example, in colon adenocarcinoma (CAC), COL1A2, THBS2, and COL1A1 were related to prognosis." (PMID 33178362, 2020).
communicating hydrocephalus (4 papers, 2019 to 2021). An abnormal accumulation of cerebrospinal fluid within the ventricles of the brain that occurs as a consequence of impaired cerebrospinal fluid reabsorption by the arachnoid granulations. "Osteogenesis imperfecta, which is caused by mutations in the type 1 procollagen genes (COL1A1/COL1A2), is associated with communicating hydrocephalus." (PMID 31575827, 2019).
depression (4 papers, 2023 to 2025). "Recent studies have revealed that Col1a2 plays a key role in depression." (PMID 39295096, 2024).
dilated cardiomyopathy (4 papers, 2021 to 2025). Cardiomyopathy which is characterized by dilation and contractile dysfunction of the left and right ventricles. "Abnormal development and functioning of the heart that results from mutations in ECM-related genes may lead to dilated cardiomyopathy and hypoplastic left heart syndrome, such as COL25A1 or COL1A2." (PMID 39202774, 2024). "Notably, among these proteins, MYL2, ACTN1, MYLK, COL1A2, COL6A2, and COL6A3 have been associated with dilated cardiomyopathy and hypertrophic cardiomyopathy pathogenic processes in previous studies." (PMID 37649075, 2023).
fibrosarcoma (4 papers, 2020 to 2024). A malignant mesenchymal fibroblastic neoplasm affecting the soft tissue and bone. "Omar Ret al., reported that COL1A2 affects cell migration of fibrosarcoma and chondrosarcoma by acting on TBX3." (PMID 33193601, 2020). "Notable, among these fusions are in-frame fusions of the collagen genes (exon 6 COL1A2, exon 20 COL1A2 and exon 35 COL3A1) with exon 2 of PDGFB in tumors of the H2 fibrosarcoma cluster which was associated with extracellular matrix and G-protein coupled receptor signaling pathways." (PMID 37369741, 2023). "TBX3 directly binds to and activates collagen type I alpha 2 chain (COL1A2), mediating the inhibitory effect of TBX3 on fibrosarcoma cell migration." (PMID 38965548, 2024). "TBX3 is regulated by AKT1 and plays a cancer-suppressive role in fibrosarcoma; TBX3 directly binds to the promoter of COL1A2, inhibiting substrate-dependent and non-substrate-independent cell proliferation, migration, and in vivo tumorigenic capacity." (PMID 38965548, 2024).
Hypodontia (4 papers, 2012 to 2021). The absence of five or less teeth from the normal series by a failure to develop. "An interesting case with familial tooth agenesis and spontaneous DGI was reported to be caused by the maternal PAX9 (c.43T>A, p.(Phe15Ile)) and de novo COL1A2 (c.1171G>A, p.(Gly391Ser)) mutations, respectively." (PMID 34201399, 2021). "A spontaneous novel mutation in COL1A2 (c.1171G>A; p.Gly391Ser) causing only dentin defects and a novel mutation in PAX9 (c.43T>A; p.Phe15Ile) causing hypodontia were identified and correlated with the phenotypic presentations in the family." (PMID 23227268, 2012). "In that study, treatment with BPs was not considered; instead, the very high prevalence of hypodontia and oligodontia prompted the group to investigate whether mutations in genes other than those earlier associated with OI (COL1A1, COL1A2, and CREB3L1) were responsible for the disturbances." (PMID 33743023, 2021).
idiopathic osteoporosis (4 papers, 2016 to 2022). "Mutations in COL1A2 are associated with osteogenesis imperfecta types II-IV, Ehlers–Danlos syndrome, and idiopathic osteoporosis." (PMID 35804365, 2022). "For example, mutations in COL1A2 can give rise to OI, EDS type VIIB, recessive EDS Classical type, idiopathic osteoporosis, and atypical Marfan syndrome." (PMID 33974636, 2021).
osteogenesis imperfecta type 2 (4 papers, 2021 to 2024). Osteogenesis imperfecta type II is a lethal type of osteogenesis imperfecta (OI), a genetic disorder characterized by increased bone fragility, low bone mass and susceptibility to bone fractures. "Duo WES of the fetus and biological father revealed a heterozygous splicing variant (NM_000089.3:c.2133 + 5 G > A) in COL1A2 (MIM 120160) that was associated with osteogenesis imperfecta Type II (MIM 166210)." (PMID 36577754, 2022). "The observed phenotype of Col1a1fapKO mice is analogous to the human type II Osteogenesis Imperfecta, which is lethal in the perinatal period due to critical genetic defects in COL1A1 or COL1A2 resulting in multiple rib and/or long bone fractures." (PMID 34893625, 2021).
scoliosis (4 papers, 2023 to 2025). A congenital or acquired spinal deformity characterized by lateral curvature of the spine. "Patients with pathogenic variants in COL1A1 or COL1A2 alone tended to have a milder form of scoliosis." (PMID 37730650, 2023). "Since patients with COL1A1 and COL1A2 variants together constituted about 2/3 of the cohort, we asked if scoliosis severity was differentially affected by the two genes." (PMID 37730650, 2023). "Within the two collagen genes, COL1A2 was less damaging than COL1A1 in progressing into advanced stages of scoliosis." (PMID 37730650, 2023). "We found that patients with COL1A1 and COL1A2 genotypes were strongly biased towards having mild or no scoliosis at all, whereas patients with pathogenic variants on IFITM5, WNT1 and other recessive genes did not display such a pattern." (PMID 37730650, 2023). "Patients with either COL1A1 and COL1A2 were strongly biased toward having mild or no scoliosis, whereas patients with mutations in IFITM5, WNT1 and other recessive genes were more evenly distributed among the four outcome grades." (PMID 37730650, 2023). "We found that COL1A2 appeared significantly less severe than COL1A1, with an OR of 0.28 (95% CI 0.1–0.71, p = 0.01) for progression into moderate or severe scoliosis." (PMID 37730650, 2023). "Fifty-four of the 69 (78.3%) COL1A2 patients were non-scoliotic or mildly scoliotic, while only 8 and 7 had moderate and severe scoliosis, respectively." (PMID 37730650, 2023). "To investigate the impact of the A429V mutation and the role of POC5 in the differentiation and function of primary osteoblasts derived from healthy donors without scoliosis and AIS patients, we performed alizarin red staining, alkaline phosphatase, and Western blot analyses of COL1A2." (PMID 37239471, 2023).
amoebiasis (3 papers, 2019 to 2022). "FN1 and COL1A2 were both enriched in PI3K-Akt signaling pathway (hsa04151), amoebiasis (hsa05146), and focal adhesion (hsa04510)." (PMID 36398072, 2022). "The prime module in protein-protein interaction network of DEGs, including ADAMTS2, COL10A1, COL1A1, COL1A2, COL8A1, BGN, and SPP1, was enriched in protein digestion and absorption, ECM-receptor interaction, focal adhesion, PI3K-Akt signaling pathway, and amoebiasis." (PMID 35726219, 2022). "In detail, COL1A2, COL1A1, and COL10A1 were enriched in protein digestion and absorption; COL1A2, COL1A1, and SPP1 were enriched in ECM-receptor interaction, focal adhesion, and PI3K-Akt signaling pathway; COL1A2 and COL1A1 were further enriched in amoebiasis (P < 0.05)." (PMID 35726219, 2022). "In addition, the up-regulated DEGs were significantly enriched in 12 pathways such as NF-kappa B signaling pathway including LYN, LY96, CCL4, CD14; ECM-receptor interaction pathway including CD44, COL6A3, COL1A2, FN1 and Amoebiasis pathway including COL1A2, ITGB2, CD14, FN1." (PMID 31355054, 2019).
asthma (3 papers, 2022 to 2025). "Zhong and colleagues confirmed that miR-98-5p promoted COL1A2 inducing extracellular matrix deposition and contributing to asthma pathogenesis in human." (PMID 37187956, 2023). "Based on ACQ at T12, statistically significant lower levels of COL1A2 in bronchial biopsies at T0 were observed in patients with ACQ < 1.5 (considered as controlled asthma)." (PMID 35534846, 2022). "The reanalysis also revealed the coexpression of SCF (KITLG) and COL1A2 in human lung fibroblasts, confirming the expression of SCF in human fibroblasts during asthma." (PMID 40674143, 2025). "In conclusion, our study revealed that BT was effective in 81% of patients irrespective of asthma endotypes and was associated with a reduction in ACTA2 and an increase in FAP, COL1A1, COL1A2 and CD68 gene expression." (PMID 35534846, 2022).
glaucoma (3 papers, 2015 to 2025). Increased pressure in the eyeball due to obstruction of the outflow of aqueous humor. "Through literature review, several key glaucoma-related genes were identified, including MYOC, TBK1, COL1A1, COL1A2, FOXC1, LRP2, OPTN, and TEK." (PMID 40808675, 2025). "Interestingly, these glaucoma-related genes like MYOC, TBK1, COL1A1, COL1A2, FOXC1, LRP2, and TEK also showed significant differential expression in RCC tissues." (PMID 40808675, 2025). "The overexpression of certain collagen genes (COL1A1 and COL1A2) in RCC suggests a role in extracellular matrix (ECM) remodeling, a critical factor in tumor metastasis, as well as in the structural changes observed in glaucoma." (PMID 40808675, 2025).
Hyperglycemia (3 papers, 2021 to 2025). An increased concentration of glucose in the blood. "Taken together, these findings in tissue-specific cells show that hyperglycemia converges on major insulin, lipid, and fibrosis pathways by DNA methylation to regulate the expression of core genes that consist of but are unlikely to be limited to MTOR, RPTOR, IRS2, TXNRD1, LCAT, SMPD3, and COL1A2." (PMID 36633903, 2023).
laryngeal carcinoma (3 papers, 2018 to 2023). Carcinoma that arises from the laryngeal epithelium. "In patients with laryngeal cancers, methylation of p16 and COL1A2 promoters were associated with poor survival (OR = 4.55, 95% CI: 1.36–15.2, p = 0.013 and OR = 3.12, 95% CI: 1.08–8.99, p = 0.035, respectively)." (PMID 29361757, 2018). "Methylation of COL1A2 was also shown to be correlated with poor survival for both hypopharyngeal and laryngeal cancer." (PMID 37835379, 2023). "The methylation of p16 and COL1A2 were independent prognostic factors for poor survival in laryngeal cancer (hazard ratio: 4.55; p = 0.013 and 3.12; p = 0.035, respectively)." (PMID 29361757, 2018). "The COL1A2 methylation status may, therefore, serve as an important site-specific biomarker for the prediction of clinical outcomes in patients with hypopharyngeal and laryngeal cancers." (PMID 29361757, 2018). "Interestingly, we found a strong association between the methylation levels of COL1A2 and disease-free survival (DFS) in hypopharyngeal and laryngeal cancers, but not in oral cavity cancers." (PMID 29361757, 2018).
liver cancer (3 papers, 2022 to 2023). An epithelial or non-epithelial malignant neoplasm that arises from the liver. "Importantly, DHA prevents and reverses fibrosis in a NASH mouse model and decreases expression of two out of three collagen encoding genes (COL1A1, COL1A2, COL4A1) that are upregulated in liver cancer and NASH." (PMID 37859621, 2023). "Based on the analysis of 367 liver cancer patients from The Cancer Proteome Atlas (TCGA) database, the COL1A1 and COL1A2 signatures showed modest correlation with ITGA2 (R = 0.49, p < 2.2e-16, R = 0.51, p < 1.7e-12, Pearson’s correlation)." (PMID 35322024, 2022).
muscular dystrophy (3 papers, 2019 to 2022). Muscular dystrophy (MD) refers to a group of more than 30 genetic diseases characterized by progressive weakness and degeneration of the skeletal muscles that control movement. "For example, it identified a pathway connecting the source protein DNAJB6, a chaperone that is causal gene for limb-griddle muscular dystrophy, and the target gene COL1A2 that was shown to be upregulated in muscular dystrophy patients." (PMID 31114913, 2019).
neuroblastoma (3 papers, 2011 to 2024). Neuroblastoma (NB) is the most common solid, extracranial childhood tumor. "We analyzed the expression of endothelial markers (EGFL7, FLT1, PTPRB33), mesenchymal cells (COL1A2, COL1A1, PDGFRB34,35) and immune markers (ITGAM, CD247, PTPRC36–38) in MYCN-amplified neuroblastoma patient samples (with at least 90% tumor purity) and tumors from Protocol #4." (PMID 39367051, 2024). "We present eight genes (KRT19, PRKCDBP, SCNN1A, POU2F2, TGFBI, COL1A2, DHRS3 and DUSP23) that are methylated in neuroblastoma, most of them not previously reported as such, some of which also distinguish between biological subsets of neuroblastoma tumors." (PMID 21314941, 2011).